SLCO4A1-AS1 (SLCO4A1 antisense RNA 1)
Synonyms: DAMER
Gene: Long non-coding RNA gene on chromosome 20 (62,663,019 to 62,666,724, reverse strand). Ensembl gene ENSG00000232803.
Diseases named in the same sentence as SLCO4A1-AS1 in open-access papers:
SLCO4A1-AS1 is named in the same sentence as 2 diseases in open-access papers, as found by Europe PMC text mining. Sharing a sentence is not in itself a finding about the gene and the disease. The quoted sentences say what the papers report.
gastric cancer (1 paper, 2021). A primary or metastatic malignant neoplasm involving the stomach. "Recently, long noncoding RNA SLCO4A1 antisense RNA 1 (SLCO4A1-AS1) has been shown to act as an oncogene in several cancer types; however, its role in gastric cancer (GC) and its underlying molecular mechanisms are yet to be elucidated." (PMID 34650909, 2021).
SLCO4A1-AS1 also shares sentences with these, for which no sentence is quoted: cancer (1 paper).